LMOD3 (leiomodin 3)
Description:
Essential for the organization of sarcomeric actin thin filaments in skeletal muscle. Increases the rate of actin polymerization.
Synonyms: NEM10
Tractability: PROTAC: UniProt records ubiquitination sites on it.
Gene: Protein-coding gene on chromosome 3 (69,106,065 to 69,123,032, reverse strand). Ensembl gene ENSG00000163380.
Subcellular location: Cytoplasm; Cytoplasm, myofibril, sarcomere, M line; Cytoplasm, myofibril, sarcomere, A band; Cytoplasm, cytoskeleton
Gene Ontology:
Molecular function: actin monomer binding; protein binding; tropomyosin binding; actin binding
Biological process: actin nucleation; positive regulation of skeletal muscle fiber development; skeletal muscle thin filament assembly; striated muscle contraction; actin filament organization; muscle contraction; myofibril assembly; skeletal muscle fiber development; pointed-end actin filament capping; striated muscle cell development
Cellular component: cytoplasm; M band; striated muscle thin filament; cytoskeleton; A band
Genetic constraint (gnomAD): Loss-of-function variants: 28 observed, 40.5 expected, observed/expected ratio (o/e) 0.69, 90% interval 0.51 to 0.95. The upper end of that interval is the gene's LOEUF score, 0.95, which puts it in group 4 of 6, group 1 being the genes least tolerant of losing a copy. Missense variants: 704 observed, 679.63 expected, observed/expected ratio (o/e) 1.04, 90% interval 0.97 to 1.1. Synonymous variants: 273 observed, 241.8 expected, observed/expected ratio (o/e) 1.13, 90% interval 1.02 to 1.25.
Gene-disease validity (ClinGen):
ClinGen rates the evidence that LMOD3 causes each of these diseases.
nemaline myopathy 10 (autosomal recessive): Definitive. Any nemaline myopathy in which the cause of the disease is a mutation in the LMOD3 gene.
Homologues: Orthologues: chimpanzee LMOD3 (99% identical), macaque LMOD3 (97% identical), dog LMOD3 (87% identical), pig LMOD3 (87% identical), rabbit LMOD3 (85% identical), guinea pig LMOD3 (84% identical), rat Lmod3 (81% identical), mouse Lmod3 (81% identical), tropical clawed frog lmod3 (58% identical), Drosophila melanogaster tmod (19% identical), Caenorhabditis elegans unc-94 (16% identical). Paralogues in human: LMOD2 (35% identical), LMOD1 (33% identical), TMOD2 (23% identical), TMOD1 (23% identical), TMOD4 (22% identical), TMOD3 (22% identical).
Diseases named in the same sentence as LMOD3 in open-access papers:
LMOD3 is named in the same sentence as 12 diseases in open-access papers, as found by Europe PMC text mining. Sharing a sentence is not in itself a finding about the gene and the disease. The quoted sentences say what the papers report.
nemaline myopathy (16 papers, 2015 to 2025). Nemaline myopathy (NM) encompasses a large spectrum of myopathies characterized by hypotonia, weakness and depressed or absent deep tendon reflexes, with pathologic evidence of nemaline bodies (rods) on muscle biopsy. "Within the leiomodin protein family, Lmod1 is smooth muscle restricted, loss of cardiac Lmod2 induces dilated cardiomyopathy in mice and mutations in Lmod3 can cause nemaline myopathy in humans and mice." (PMID 35148320, 2022). "Consistent with neonatal death of patients with LMOD3-associated nemaline myopathy, lmod3sa13018 homozygotes died prematurely before 12 dpf." (PMID 35148320, 2022). "A hallmark of dysfunctional LMOD3 in nemaline myopathy patients is the formation of nemaline bodies (rods), aggregates of actin and α-actinin typically marked by Gomori trichrome staining and detected as electron-dense structures on electron micrographs." (PMID 35148320, 2022). "Sarcomere organisation within lmod3sa13018 myofibres was compromised and aberrant α-actinin- and actin-positive aggregates were detected along with electron-dense structures, which resemble nemaline bodies found in LMOD3-deficient nemaline myopathy." (PMID 35148320, 2022). "LMOD3, the gene encoding leimodin-3, a sarcomeric actin nucleator, was identified as a cause of nemaline myopathies." (PMID 34433058, 2021). "In turn, KLHL40 is suggested to stabilize nebulin and Leimodin 3 (LMOD3, another protein implicated in nemaline myopathy) by acting like a chaperone and maintaining proper folding of these two proteins during muscle contraction." (PMID 32660935, 2020). "LMOD3 biopsies have been reported to show rods with a fringe of myofibrils attached, but we have observed similar rods associated with other nemaline myopathy gene mutations, in particular KLHL40." (PMID 31228046, 2019). "The mutant mice display disorganized sarcomere and the presence of nemaline bodies in skeletal muscles, a hallmark of the disease nemaline myopathy (NM), consistent with the finding that LMOD3 is mutated in the NM patients." (PMID 27274810, 2016). "In seven patients with nemaline myopathy, the authors identified several causal variants in the ACTA1 gene (in one patient), the LMOD3 gene (in two patients), the PLOD1 gene (in one patient), and the NEB gene (in four patients)." (PMID 37989827, 2024). "Mouse models of LMOD3 nemaline myopathy showed atrophy of fibres with fast myosin, a 50% reduction of grip strength, small body size and normal lifespan." (PMID 31228046, 2019). "Highlighted Article: A leiomodin-3 mouse mutant generated by insertion of the piggyBac transposon exhibits nemaline myopathy with fast-myofiber-specific atrophy." (PMID 26035871, 2015). "Dysfunctional LMOD3 in nemaline myopathy patients leads to muscle weakness." (PMID 35148320, 2022). "Mutations in ten different genes cause nemaline myopathy: skeletal muscle α-actin (ACTA1), nebulin (NEB), α-tropomyosin, β-tropomyosin, troponin T1, cofilin 2 (CFL2), KBTBD13, KLHL40, KLHL41 and leiomodin 3 (LMOD3)." (PMID 25931053, 2015).
cardiomyopathy (1 paper, 2017). A disease of the heart muscle or myocardium proper. "In contrast to LMOD3, LMOD2, another member of the LMOD family involved in thin filament shortening and cardiomyopathy, was also up-regulated in Klhl41 KO mice both at protein and mRNA levels." (PMID 28826497, 2017).
Stroke (1 paper, 2025). Sudden impairment of blood flow to a part of the brain due to occlusion or rupture of an artery to the brain. "Six days post-stroke, differentially expressed thin filament proteins were annotated as follows: Ablim1, Pdlim1, Lmod2, Dbnl, Parvb, Pdlim3, Tpm2, parvin alpha (Parva), and destrin (Dstn) were upregulated, while Lmod3 was downregulated." (PMID 41226396, 2025).
neuromuscular disease (1 paper, 2015). "The study has also resulted in the identification of four novel neuromuscular disease genes, and has led to the identification of a novel mechanism of sarcomere assembly and muscle dysfunction involving KLHL40, KLHL41 and LMOD3." (PMID 26578207, 2015).
tumour (1 paper, 2021). "Indeed, several downstream targets of MEF2 involved in muscle structure and function were among the top FoxP1 target genes repressed in response to tumour burden, including Casq1, Casq2, Lmod3, Ky, and Mef2c —suggesting that FoxP1 up‐regulation disrupts MEF2 transcriptional activity." (PMID 33527776, 2021).
LMOD3 also shares sentences with these, for which no sentence is quoted: autosomal recessive nemaline myopathy (1 paper); cervical cancer (1); congenital myopathy (1); congenital nemaline myopathy (1); diaphanospondylodysostosis (1); limb-girdle muscular dystrophy (1); myopathy (1).